TMEM238L (transmembrane protein 238 like)
Description:
May play a role in inducing apoptosis during endoplasmic reticulum (ER) stress and in the inhibition of proliferation and tumorigenicity.
Synonyms: FORCP; LINC00675
Tractability: Antibody: UniProt predicts a signal peptide or a membrane-spanning region.
Gene: Protein-coding gene on chromosome 17 (10,794,908 to 10,804,099, reverse strand). Ensembl gene ENSG00000263429.
Subcellular location: Endoplasmic reticulum membrane
Gene Ontology:
Molecular function: protein binding
Biological process: intrinsic apoptotic signaling pathway in response to endoplasmic reticulum stress
Cellular component: endoplasmic reticulum membrane
Homologues: Orthologues: chimpanzee TMEM238L (99% identical), dog TMEM238L (77% identical), pig TMEM238L (76% identical), rat Tmem238l (75% identical), mouse Tmem238l (71% identical), rabbit TMEM238L (62% identical).
Diseases named in the same sentence as TMEM238L in open-access papers:
TMEM238L is named in the same sentence as 15 diseases in open-access papers, as found by Europe PMC text mining. Sharing a sentence is not in itself a finding about the gene and the disease. The quoted sentences say what the papers report.
colorectal cancer (5 papers, 2018 to 2023). A primary or metastatic malignant neoplasm that affects the colon or rectum. "LINC00675 (also known as TMEM238L) has been shown to be dysregulated and as a prognostic predictor in gastric cancer, colorectal cancer and pancreatic cancer." (PMID 30061182, 2018). "For instance, LINC00675, also known as TMEM238L, has been reported to be dysregulated in several cancers, including gastric cancer, colorectal cancer and cervical cancer." (PMID 36674820, 2023).
colon cancer (1 paper, 2025). "Notably, TMEM220-AS1, TMEM238L, SOX6, SMAD7, TCF7L2, and PYGL were significantly downregulated in colon cancer, whereas LINC02257, PCAT1, CASC8, and POU5F1B were significantly upregulated in colon cancer." (PMID 41144378, 2025).
cancer (9 papers, 2018 to 2023). A tumor composed of atypical neoplastic, often pleomorphic cells that invade other tissues. "LINC00675 is also known as TMEM238L, and it has been reported to be dys-regulated in many cancers." (PMID 33489916, 2020).
TMEM238L also shares sentences with these, for which no sentence is quoted: tumor (7 papers); gastric cancer (5); hepatocellular carcinoma (4); cervical cancer (3); glioma (3); esophageal squamous cell carcinoma (2); pancreatic cancer (2); prostate carcinoma (2); breast carcinoma (1); lymph node metastasis (1); metastatic colorectal cancer (1); ovarian carcinoma (1).